SNIP1 (Smad nuclear interacting protein 1)
Diseases named in the same sentence as SNIP1 in open-access papers (continued):
Sharing a sentence is not in itself a finding about the gene and the disease.
tumor (9 papers, 2017 to 2025). "Taken together, these results demonstrate that KMT5A-dependent SNIP1 methylation promotes TNBC tumor and lung metastasis by activating MARK4 transcription and subsequent modification of the Hippo/YAP signaling pathway." (PMID 35449131, 2022). "Smad nuclear-interacting protein 1 (SNIP1) is a transcription repressor related to the TGF-β signaling pathway and associates with c-MYC, a key regulator of cell proliferation and tumor development." (PMID 35449131, 2022). "SNIP1 is a transcription regulator contains a nuclear localization sequence, and plays a key role in tumor development and progression." (PMID 33150075, 2020). "Moreover, miR-29a-3p mediated its tumor-suppressive activity and suppressed the tumorigenicity in HeLa cells by directly targeting smad nuclear interacting protein 1 (SNIP1)." (PMID 35879698, 2022). "In 2014, Yang reported on the lncRNA BCAR4 (breast-cancer anti-estrogen resistance 4), which simultaneously binds to the transcription factor SNIP1 (Smad nuclear interacting protein 1) and the phosphatase 1 nuclear- Targeting subunit (PNUTS), and it regulates the hedgehog/GLI2 signaling pathway." (PMID 28212533, 2017). "This study reported for the first time that the expression of MKRN1 and SNIP1 in CRC were negatively correlated, confirming that SNIP1 can act as a tumour suppressor and can be modified by MKRN1 ubiquitination at the protein level." (PMID 37620897, 2023). "Tumour tissue was used for IHC analysis, which revealed high MKRN1 and TGF-β1 expression and low SNIP1 and E-cadherin expression in the cancer cells." (PMID 37620897, 2023).
cancer (5 papers, 2017 to 2023). A tumor composed of atypical neoplastic, often pleomorphic cells that invade other tissues. "Currently, the mechanism by which SNIP1 regulates tumorigenesis and cancer metastasis is unknown." (PMID 35449131, 2022). "High MKRN1 levels promote TGF-β signalling through ubiquitination and degradation of SNIP1, thereby facilitating CRC metastasis, and supporting MKRN1 as a CRC pro-cancer factor." (PMID 37620897, 2023). "For the positive–negative subjects (screening), 3 CNAs were detected in BC genes (ACVR2A, CUL3 and PIK3R1), and 5 SNPs were identified in 6 non-BC cancer genes (SNIP1, TBC1D10B, PANK1, PRKCA and RUNX2; SUPT3H)." (PMID 35589867, 2022). "Importantly, this study reveals that KMT5A-mediated SNIP1 K301 methylation not only serves as a key signal driving c-MYC hyper-activation and cancer metastasis, but also acts as a marker of poor prognosis of TNBC patients." (PMID 35449131, 2022). "Moreover, whether SNIP1 methylation occurs, and regulates oncogenic signaling, as well as is involved in TNBC cancer metastasis, remains to be investigated." (PMID 35449131, 2022).
infection (2 papers, 2016 to 2023). The state of being infected such as from the introduction of a foreign agent such as serum, vaccine, antigenic substance or organism. "On the other hand, overexpression of SNIP1 in NRCMs by AdSNIP1 infection could inhibit Ang II‐induced activation of the NF‐κB p65 pathway." (PMID 27912208, 2016).
neurodevelopmental disorder (2 papers, 2021 to 2023). A behavioral and cognitive disorder with onset during the developmental period that involves impaired or aberrant development of intellectual, motor, or social functions. "Here, we describe extensive genetic studies and clinical findings of a complex inherited neurodevelopmental disorder in 35 individuals associated with a SNIP1 NM_024700.4:c.1097A>G, p.(Glu366Gly) variant, present at high frequency in the Amish community." (PMID 34570759, 2021). "Here, we describe our studies of a complex syndromic autosomal recessive neurodevelopmental disorder due to a biallelic SNIP1 variant (NM_024700.4:c.1097A>G, p.(Glu366Gly)), which we found to be common amongst the Old Order Amish." (PMID 34570759, 2021). "Mutations in SNIP1 has also been linked to neurodevelopmental disorders." (PMID 37553330, 2023). "Here we present comprehensive genetic, clinical and gene transcript functional outcomes stemming from the investigation of 35 Amish individuals with an autosomal recessive neurodevelopmental disorder, corroborating this SNIP1 gene variant as a cause of this disease." (PMID 34570759, 2021). "Taken together, these findings consolidate biallelic variants within the SNIP1 gene as a cause of a complex neurodevelopmental disorder and provide important insight into the biological role and key molecular processes perturbed by pathogenic variation of SNIP1." (PMID 34570759, 2021).
cardiac disease (1 paper, 2024). "For example, some genes, such as SNIP1 and SHROOM3, have only recently been linked to cardiac disease; so, prior to this, pathogenic variants in these genes may have been unreported or considered incidental findings in patients undergoing testing for cardiac indications." (PMID 38731073, 2024).
SNIP1 also shares sentences with these, for which no sentence is quoted: colorectal cancer (3 papers); Intellectual disability (3); glioma (2); ovarian carcinoma (2); aortic coarctation (1); aortic root dilatation (1); aortic stenosis (1); atrial septal defect (1); Bicuspid aortic valve (1); breast (1); cardiomyopathy (1); cerebrocostomandibular syndrome (1); cleft palate (1); endocervical adenocarcinoma (1); fibrosis (1); genetic disease (1); Guion-Almeida type mandibulofacial dysostosis (1); hypertrophy (1); hypoplastic left heart syndrome (1); inflammatory bowel disease (1); left ventricular noncompaction (1); microcephaly (1); mitral valve regurgitation (1); Nager syndrome (1); non-small cell lung carcinoma (1); Patent ductus arteriosus (1); Pulmonary artery stenosis (1); Rolandic epilepsy (1); scoliosis (1); Tetralogy of Fallot (1).
A further 1 disease shares a sentence with SNIP1 in 1 paper.